IL7 (interleukin 7)
Diseases named in the same sentence as IL7 in open-access papers (continued):
Sharing a sentence is not in itself a finding about the gene and the disease.
asthma (19 papers, 2009 to 2026). "Pro-inflammatory cells, such as Il-7 and Il-3, are involved in the pathogenesis of asthma, along with the increase in Th-17 cells, causing an imbalance between Th1 and Th2 cells." (PMID 40648899, 2025). "Asthma‐associated rs3194051 is a lung m6A QTL for immune‐related interleukin‐7 (IL‐7) that contributes to atopic asthma, acting in bronchoalveolar lavage fluid and regulating airway eosinophilia." (PMID 34647423, 2021). "TSLP, a general biomarker for skin-barrier defects, is an interleukin-7 (IL-7)–like cytokine produced by epithelial cells and is implicated in the pathogenesis of both AD and asthma." (PMID 19557146, 2009). "Another asthma‐specific target is IL‐7R, which acts as a receptor for interleukin‐7 (IL‐7) and TSLP." (PMID 37186423, 2023). "IL-7 signalling has been suggested to promote the immunopathogenesis of asthma, indicating the potential informativity of the identified CpGs on asthma acquisition." (PMID 35207690, 2022). "IL-7 is considered to activate eosinophils and has a pivotal function in allergic inflammation in asthma, but is also essential for T- and B-cell development." (PMID 34737744, 2021). "It is well recognized that asthma is an immune response driven by Th2 and Th17 cells with cytokines such as IL-4, IL-5, IL-9, IL-10, IL-13, and IL-7 playing important roles." (PMID 33123005, 2020). "Further study is needed to investigate the contribution of IL-7 to T cell-mediated chronic inflammatory diseases such as steroid-resistant asthma." (PMID 29951134, 2018). "Complimentary studies revealed that IL-7 was increased by airway epithelial cells following exposure to environmental particulates with diameters that are less 2.5 μm known to promote asthma." (PMID 25359169, 2014). "Specifically, smokers with asthma had raised IL-6 (p<0.001), IL-7 (p = 0.033) and IL-12 (p = 0.042)." (PMID 23951170, 2013). "The dependence of ILC2s on IL-7 in asthma and the regulatory mechanism of IL-7 on ILC2 function remain unclear and need further study." (PMID 34177881, 2021). "Moreover, DAPP1 expression in the lung was highly positively correlated with a panel of pro-inflammatory cytokines, including several that have been implicated in asthma, such as IL1A, IL7, IL12A, IL17A, IL23A, and IL33." (PMID 31869344, 2019). "Compared to healthy control subjects, patients with asthma had significantly more percentages of eosinophils and neutrophils, IL-1RA, IL-1α, IL-1β, IL-2Rα, IL-5, IL-6, IL-7, IL-8, G-CSF, GROα (CXCL1), MIP-1β (CCL4), MIG (CXCL9), RANTES (CCL5) and TRAIL in their BAL fluids." (PMID 26011707, 2015). "In an experimental asthma rat model, CBD diminished airway inflammation and IL-4, IL-5, IL-13, IL-6, IL-7 and TNF-α serum levels, which contribute to fibrosis and asthma pathophysiologies." (PMID 36556483, 2022). "Among these pathways, hematopoietic cell lineage is closely related to asthma, and the mRNAs enriched in this pathway included FCER2A, GP1BA, IL-7, and CD5." (PMID 34737744, 2021). "Thus, T2-low asthma is characterized by neutrophilic airway inflammation through the involvement of non-type 2 cytokines such as IL-8 and IL7 rather than eosinophilic inflammation." (PMID 36949398, 2023).
depression (19 papers, 2018 to 2025). "Depression was also associated with the inflammatory markers (i.e., interleukin 1, 6; C‐reactive protein, while in our study, the role of IL‐7 might be more significant)." (PMID 33027558, 2020). "One research reported that levels of IL-7 is elevated in depressed subjects, while some studies found that the depression patients have significantly lower levels of IL-7 than CON." (PMID 39763672, 2024). "Some previous studies have related IL-7 to disturbed emotional function, e.g., depression and anorexia nervosa." (PMID 35628904, 2022). "IL-7 was correlated with the POMS Depression subscale (r = 0.72, p < 0.001, n = 18) and MDASI Severity (r = 0.75, p < 0.001, n = 17)." (PMID 36354718, 2022). "For example, depression was negatively related to IL-7 in the full sample, and PTSD was positively related to IL-7 in the AN sample." (PMID 34442458, 2021). "First, we found that the baseline levels of IL-10, IL-12p70, IL-13, IL-17A, IL-1β, IL-2, IL-23, IL-5, IL-6, IL-7, and MIP-1β were associated with depression symptoms." (PMID 32699226, 2020). "We found a significant association between the severity of depression rated by the HRSD-17 and the levels of the three immune markers VEGF, IL-7, and TNF in the multivariate regression model." (PMID 29940870, 2018). "A view holds that as a homeostatic cytokine regulating T cells function, IL-7/IL-7R signaling pathway is involved in the cascade possibly contributing to the hypothesized depression-related lymphokine suppression." (PMID 39763672, 2024). "IL-7 is both an active chemokine for macrophage recruitment, as well as in macrophage differentiation, and macrophages have been found to contain a pro-inflammatory profile in depression." (PMID 38297265, 2024). "IL-7 is also important in the development of depressive disorders." (PMID 35098831, 2022). "Increases in IL-15 and IL-7 might be attributed to T-cell growth, which may equate with increases in monoamine activity, even in individuals with minor reductions in depression severity." (PMID 33276697, 2020). "However, previous studies found that the levels of IL-7 are elusively in depression patients." (PMID 39763672, 2024). "In our review, we noticed that IL-7 decreased with the administration of the SSRI escitalopram (one study, moderate depression) and ketamine (one study, treatment-resistant depression)." (PMID 40573262, 2025). "Among their top 10 most significant proteins that were altered after treatment were the same proteins that we found in our OPLS and OPLS-DA models for depression and anxiety (CXCL6, STAMPB, CXCL1, SIRT2, AXIN1, CXCL5, ST1A1, and IL-7)." (PMID 36979692, 2023). "The biomarkers assessed in the studies involving depression include IL-6 (n = 5), IL-10 (n = 4), TNF-α (n = 4), IL-1β (n = 2), CRP (n = 2), and IL-7 (n = 1)." (PMID 35053845, 2022). "Levels of prenatal cytokines (IL-1, IL-5, IL-7, MPI-1α, GM-CSF, MCP, MIB) were not statistically different when participants were grouped as either low-high stress, yes-no fatigue, or yes-no depression." (PMID 40682534, 2025). "IL-7 is tentatively higher in participants with a primarily somatic subtype at baseline, while IL-6 and SAA decrease over time in those with a somatic but not cognitive subtype of depression." (PMID 33276697, 2020).
glioma (19 papers, 2010 to 2025). A benign or malignant brain and spinal cord tumor that arises from glial cells (astrocytes, oligodendrocytes, ependymal cells). "Peripheral administration of long-acting IL-7 has been shown to enhance T cell accumulation in murine glioma and boosts the efficacy of T cell engagers against solid tumors." (PMID 40244705, 2025). "We concluded then that nonantigen specific, exogenously administered CD8+ T cells can indeed accumulate within gliomas, despite tumor-imposed T cell sequestration, with IL-7 ALT accumulating intratumorally at a greater rate than IL-2–ALT." (PMID 40244705, 2025). "Another phase I clinical trial also studied the use of IL-7 in glioma patients after chemoradiotherapy, and preliminary results showed a dose-dependent increase in absolute lymphocyte counts upon IL-7 administration." (PMID 39315059, 2024). "Administration of IL-7 in mouse glioma models was observed to mitigate RIL via increasing both systemic and tumour CD8+ T cells, which presumably led to increased mouse survival." (PMID 39315059, 2024). "Reportedly, MSCs loaded with paclitaxel, miRNA, IL12/IL7 or oncolytic virus can prolong the survival of glioma-bearing mice." (PMID 37481646, 2023). "It is worth mentioning that SINV carrying IL-7 and IL-12 had the most notable glioma-killing effect." (PMID 37835433, 2023). "This therapy is in an ongoing clinical trial (NCT03687957) of intramuscular injections of modified IL7 in gliomas with irradiation/TMZ administration." (PMID 36817432, 2023). "Subsequently, to further explore the regulation of STAT5A on the transcription of LINC01198, glioma cells were stimulated with recombinant human IL-7." (PMID 32246817, 2020). "In a human glioma cancer model, the expression of IL-7 was positively correlated with the IC50 of cisplatin in both cell lines and glioma patient samples, and the overexpression of IL-7 further increased cisplatin resistance in glioma cancer cells." (PMID 30791601, 2019). "IL7 expression in glioma cell lines and tumor samples positively correlated to the extent of chemoresistance to cisplatin and thereby suggesting its importance in clinical management of glioma." (PMID 26390214, 2015). "Peripheral vaccination using N32 rat glioma cells transduced with IFN-γ and interleukin 7 induced intracranial rejection of the parental N32 glioma." (PMID 21437175, 2010). "Interestingly, while combination IL-7 ALT + αPD-1 therapy exhibited a limited survival benefit in the CT2AvIII glioma model, greater efficacy was observed in mice bearing more immunogenic GL261 gliomas." (PMID 40244705, 2025). "IL-7 ALT synergizes with T cell–centric immunotherapies in orthotopic glioma models." (PMID 40244705, 2025). "In glioma models, the use of IL7 is beginning to be explored." (PMID 36817432, 2023). "Furthermore, in an intracranial glioma model, SINV containing IL-7 and IL-12 effectively prolonged the survival time of mice and inhibited glioma progression." (PMID 37835433, 2023). "Indeed, IL-7 in combination with IFN-γ significantly increased the survival time in an animal model for glioma." (PMID 34654395, 2021). "IL-7, IL-8, and GRO/CXCL1 have each been implicated in glioma biology." (PMID 30379898, 2018). "Combination IL-7 ALT and T cell–centric immunotherapies increase survival in multiple models of glioma." (PMID 40244705, 2025). "IL-7, IL-8, GRO/CXCL1 and VEGF were informative in distinguishing WHO grade III and IV gliomas from the other disease states studied." (PMID 30379898, 2018). "Gliomas can also be distinguished from autoimmune/demyelinating disorders by higher levels of GRO/CXCL1 (p = 0.0044), IL-7 (p = 0.0035) and IL-8 (p = 0.0176)." (PMID 30379898, 2018). "Pretreatment with IL-7 ALT also enhanced the efficacy of multiple tumor-specific and nontumor-specific T cell–dependent immunotherapies against orthotopic murine and human xenograft gliomas." (PMID 40244705, 2025).
glioma (continued). "Based on these findings, we concluded that: (a) IL-7 exposure increases the expression of VLA-4 on CD8+ T cells and (b) VLA-4 expression and signaling are necessary for the enhanced accumulation of IL-7 ALT CD8+ T cells in glioma." (PMID 40244705, 2025). "It has been shown that by means of tumour-specific tropism of MSCs can be transduced to deliver anticancer agents such as interleukins (IL-2, IL-7, IL-18, and IL-12), TRAIL, and interferon (IFN-β and IFN-γ) directly to glioma sites to kill tumour cells or to regulate immune responses." (PMID 32981013, 2020).
pancreatic cancer (18 papers, 2013 to 2025). "We successfully constructed a human vaccinia virus containing human GM-CSF and IL-7 and validated its therapeutic effect in the hamster pancreatic cancer model." (PMID 40299475, 2025). "In pancreatic cancer, Tbeta10 stimulates secretion of proinflammatory cytokines interleukin (IL-7) and IL-8, which may promote pancreatic cancer pathogenesis and progression." (PMID 25037578, 2014). "In reference to IL-7/CCL19-engineered mesothelin-redirected CAR-Ts, it was reported that the adoptive transfer of these CAR-Ts to a pancreatic cancer patient led to the complete elimination of tumors almost 8 months following CAR-T treatment." (PMID 38146364, 2023). "The development of strategies based on immunonutrition, recombinant IL-7, to expand CD4 T cells and the preliminary results of novel immunotherapies, offer new therapeutic endpoints to be assessed in pancreatic cancer patients." (PMID 27782813, 2016). "A phase 1 clinical trial (NCT03198546) evaluating CAR-T cells with constitutive expression of IL-7 and CCL19 in six patients with progressive hepatocellular carcinoma, pancreatic carcinoma, and ovarian carcinoma expressing either GPC3 or MSLN showed promising results." (PMID 41154636, 2025). "In another study, the intravenous injection of interleukin 7 (IL-7) and Chemokine (C-C motif) ligand-19 (CCL19)-MSLN secreting CAR-T cells (NCT03198546) in a patient with advanced pancreatic cancer induced complete regression of the tumor 240 days post-treatment." (PMID 36717905, 2023). "Moreover, these researchers reported that adoptive transfer of their IL-7/CCL19-engineered CAR-Ts mediated strong tumor regression in xenograft models of liver cancer and pancreatic cancer." (PMID 38146364, 2023). "Another ongoing clinical trial (NCT03932565) evaluates intratumoral injection of Nectin4/FAP-targeted fourth-generation CAR-T cells (expressing IL-7 and CCL19, or IL12) for the treatment of Nectin4-positive advanced malignant solid tumors (NSCLC, breast, ovarian, bladder or pancreatic cancer)." (PMID 35211124, 2022). "The same team validated the use of anti-mesothelin IL-7/CCL19-producing human CAR-T cells in a preclinical model of orthotopic pre-established malignant mesothelioma, as well as in patient derived xenograft (PTX) models of mesothelin-positive pancreatic cancer." (PMID 35211124, 2022). "Effectiveness of this strategy was demonstrated against pancreatic cancer using a PSCA-specific CAR engineered with an inverted IL-4/IL-7 chimeric cytokine receptor (4/7-ICR), which contains an IL-4 extracellular domain fused to an activating IL-7 intracellular domain." (PMID 30828333, 2019). "Most recently, IL-7– and CCL21-expressing (7 × 21) CAR T cells were reported to yield better efficacy than 7 × 19 CAR T cells in mouse solid tumor models of pancreatic carcinoma, breast cancer, and HCC without preconditional lymphodepletion." (PMID 36059449, 2022).
systemic lupus erythematosus (18 papers, 2011 to 2025). An autoimmune multi-organ disease typically associated with vasculopathy and autoantibody production. "Recent studies provided further evidence of targeting of BAFF/BLys and APRIL in the management of lupus; and another study reported the effect of hCDR1 on IL-7 and apoptosis and showed the rate of apoptosis is reduced with hCDR1 treatment in lupus mice." (PMID 34093553, 2021). "RA LNSCs specific enrichment involved pathways like Systemic lupus erythematosus (e.g., C3), cytokine signaling (e.g., IL-7) and packaging of telomere ends (e.g., histone cluster genes)." (PMID 31481955, 2019). "Recently, a therapeutic trial of three doses of recombinant IL-7 applied to increase peripheral T cell numbers in patients with T cell lymphopenia led to induction of systemic lupus erythematosus (SLE) in one out of nine patients." (PMID 28942732, 2017). "The lupus mice exhibited a significant elevation in plasma levels of IL-4, IL-6, IL-7, IL-12, IL-17, IFN-α, IFN-γ, TGF-β, BAFF and APRIL and a marked elevation of IgG2a, IgG3 and ant-dsDNA autoantibodies compared with normal healthy mice." (PMID 25909640, 2015). "In line with our results, it has recently been shown in systemic lupus erythematosus, that cAMP has suppressive activity on IL-2 and IL-7 production through epigenetic modifications in IL-2 and IL-7 promoter genes." (PMID 23658513, 2013). "In addition, the DN T cells that massively accumulate in this Fas-defective lupus model were found to permanently down-regulate the receptors for IL-7 and IL-15, probably due to chronic activation in part mediated by commensal antigens, leading to reduced consumption of these cytokines." (PMID 22102903, 2011). "Our findings revealed increased levels of IL-4, IL-6, IL-7, IL-12, IL-17, IFN-α, IFN-γ, TGF-β, BAFF and APRIL in lupus mice." (PMID 25909640, 2015). "We observed that lupus mice had aberrant and significantly elevated levels of IL-4, IL-6, IL-7, IL-12, IL-17, IFN-α, IFN-γ, TGF-β, BAFF and APRIL compared with the control non-lupus healthy mice (* P < 0.05)." (PMID 25909640, 2015). "Indeed, IL-7 administration mainly in HIV-infected or immunosuppressed patients was generally well tolerated, with a single report of a patient developing systemic lupus erythematosus after 3 doses of IL-7." (PMID 29506153, 2018).